TMEM14EP (transmembrane protein 14E, pseudogene)
Synonyms: formerly TMEM14E
Gene: Transcribed processed pseudogene on chromosome 3 (152,340,527 to 152,340,904, reverse strand). Ensembl gene ENSG00000221962.
Subcellular location: Membrane
Diseases named in the same sentence as TMEM14EP in open-access papers:
TMEM14EP is named in the same sentence as 1 disease in open-access papers, as found by Europe PMC text mining. Sharing a sentence is not in itself a finding about the gene and the disease.
TMEM14EP shares sentences with these, for which no sentence is quoted: infection (1 paper).